CD99 (CD99 molecule (Xg blood group))
Diseases named in the same sentence as CD99 in open-access papers (continued):
Sharing a sentence is not in itself a finding about the gene and the disease.
tumor (continued). "Typical findings associated with stromal sarcoma involve positive expression of vimentin, cytokeratin, CK7, CD99, Bcl-2, SS18-SSX2, and SYT-SSX in the tumor cells." (PMID 39079400, 2024). "We compared the expression levels of the CD99, CDKN1A, NES, SOX2, and TUBB3 genes in ES tumor samples and controls consisting of normal muscle tissue." (PMID 38785514, 2024). "The immunohistochemical examination demonstrated tumor cells positivity for ER, PR, WT1, Calretinin, CD56, CD99, Smooth Muscle Actin, and Desmin, with focal positivity for E-cadherin and p16." (PMID 38276058, 2024). "Up to now, immunohistochemical staining has usually shown that tumor cells differentially express CD34, BCL-2, wave proteins and CD99, which are almost always positively or strongly positively expressed in SFT." (PMID 39015488, 2024). "Our gene expression analysis indicates a reduction in the transcription of CD99 and CDKN1A and increased levels of SOX2 in ES tumors, the latter being consistent with the role of stemness in tumor progression." (PMID 38785514, 2024). "The changed signaling pathways of T cells as the communication signal source or target cell population were CD99, SELE, and HLA pathways in the tumor group compared with the normal group." (PMID 38448802, 2024). "Tumor cells were immunoreactive with a 4+ grade for the TLE1 marker in our case, along with a 3+ grade for CD99 establishing a proper diagnosis for SS." (PMID 38410005, 2024). "IHC demonstrated moderate/strong CD99 and CD117 expression in ES tumor samples, while adjacent healthy tissue had limited expression." (PMID 37568714, 2023). "This revealed several strong putative interactions between GBM tumor cell ligands and macrophage receptors that were conserved over the different co‐cultures, including APP:CD74, CD99:PILRA, PTN:ALK, and CLU:TREM2." (PMID 37791581, 2023). "The tumor was strongly positive for NKX2.2 (nuclear) and CD99 (membranous) by immunohistochemistry, and a diagnosis of ES was rendered." (PMID 37372318, 2023). "Within the tumor microenvironment, GC cells with high GADD45B expression are prominently involved in the CD99 signaling network, while those with low GADD45B expression predominantly participate in the CDH signaling network." (PMID 37608794, 2023). "During the first round of immunohistochemical stains, the tumor cells showed positivity for CD56, CD99 (diffuse to patchy), INSM1, and NKX2.2, while they were negative for desmin, cytokeratin, SS18-SSX, and WT-1." (PMID 36765856, 2023). "The tumor was strongly and diffusely positive for NKX2.2 (nuclear) and CD99 (membranous) by immunohistochemistry, and a diagnosis of ES was rendered." (PMID 37372318, 2023). "Immunohistochemical staining revealed that the tumor cells were positive for CD34, CD99, Bcl-2, and STAT6." (PMID 37491539, 2023). "Western blotting of resected tumor lysates confirmed the Dox-induced EHD1 KD in the shEHD1 group, and IHC staining with anti-human CD99 confirmed the tumor mass." (PMID 37474760, 2023). "The tumor stained positive for pancytokeratin, AE1/AE3, epithelial membrane antigen (EMA), TLE-1, CD99, and BCL-2." (PMID 38188535, 2023). "The tumor cells showed a strong immunohistochemical positivity for CD10, CD99 and INI-1, with all other applied antibodies remaining negative." (PMID 34780010, 2022). "Immunohistochemistry staining (magnification, ×400) showed that the tumor cells were positive for STAT6, CD34, Ki67 (10%), CD99, Bcl2, and Vimentin." (PMID 36386546, 2022). "For Fra-2 cl 2 primary tumours, genes such as SRGN (Serglycin) and ESAM were upregulated, while CD99 and SELPLG (selectin P ligand) were downregulated." (PMID 34693476, 2022). "The tumor showed the expression of cytokeratins, such as CK8-18 and AE1/AE3, and typical CD99 expression, whereas immunostaining for thyroglobulin, TTF1, PAX8, calcitonin, CK20, SOX10, ERG, SMA, and NUT was negative." (PMID 36129618, 2022).
tumor (continued). "For such cases, CD99 and NKX2.2 immunostaining or molecular analysis with NGS or FISH can be helpful to properly classify the tumor which is of crucial importance for proper patient management." (PMID 34312795, 2022). "The heterogeneous expression of CD99, HRNR, and CANX in both healthy and tumor tissue hampered the quantitative comparison." (PMID 35267445, 2022). "Immunohistochemistry with CD99 and EMA plays a limited role, as both benign and malignant EWSR1/FUS::NFATC2-rearranged neoplasms can stain positive." (PMID 36555836, 2022). "Tumor cells were positive with regard to the membranous and cytoplasmic expression of CD34, bcl-2, and CD99 and furthermore showed nuclear STAT6 positivity (respectively)." (PMID 36428694, 2022). "Immunohistochemistry staining (magnification, ×400) showed that the tumor cells were positive for CD34, STAT6, Ki67 (8%), CD99, and Vimentin." (PMID 36386546, 2022). "Histological features were evaluated and revealed a highly cellular tumor with positive expression of BCL2, CD34, CD99, and STAT6 proteins that are consistent with a diagnosis of SFT." (PMID 34765368, 2021). "Importantly, transwell assays showed that CD99 depletion resulted in a twofold enhancement of TEM activity compared to the control siRNA-treated cells, demonstrating that the increased spreading of the tumour cells on the EC monolayer was associated with increased TEM activity." (PMID 34374417, 2021). "The higher expression of FAM3C, LGALS9, ANXA1, SPP1, CD99 and LAMP1 in tumor tissues compared with normal tissues were confirmed by immunohistochemistry in tumors." (PMID 35087839, 2021). "CD99 positive A673 and TC32 cells were confirmed on Day 0, demonstrating that EwS tumor cells initially arrive in lungs in both strains (average area in μm2 = 8 and 18 for NSG and NOD/SCID, respectively)." (PMID 33828989, 2021). "To verify a functional interaction between CD99 and CDC42 we performed RNAi against tumour cell CD99 and CDC42, individually and in combination." (PMID 34374417, 2021). "In the immunohistochemical study, tumor cells showed positivity for CD34, CD99, and BCL2 and negativity for EMA, protein S100, and glial fibrillary acidic protein." (PMID 34211794, 2021). "However, we cannot dissociate TEM activity in this model from events occurring after seeding into the metastatic site; tumour-stromal interactions and innate immune recognition (which remains intact in the SCID mouse model) may also be regulated by tumour cell CD99 and contribute to progression." (PMID 34374417, 2021). "As CD99 expression is usually lost in the dedifferentiated SFT (in the DD zones), it is probable that CD99 would act also as a tumor suppressor in the context of SFT." (PMID 34200924, 2021). "By establishing a functional link between CD99 and CDC42 in tumour TEM, we demonstrate that CD99 plays a key role in tumour progression and implicate cell surface CD99 in controlling the diverse activities regulated by CDC42." (PMID 34374417, 2021). "We demonstrated that CD99 activation regulates actin cytoskeleton dynamics through PTPN12/FAK/Rho/Rac axis, thereby suppressing EGFR activation and relevant tumor growth." (PMID 33050232, 2020). "This indicates a high sensitivity; however, it is known that both CD99 and PAX8 are also expressed in other tumours." (PMID 32675940, 2020). "Immunohistochemical staining revealed that the tumor cells were positive for STAT6, CD34, CD99, and BCL2." (PMID 32638177, 2020). "Diffuse CD99, ERG, CD56, focal PanCK, Cam5.2 and Synaptophysin immune positivity are characteristic for Ewing sarcoma family of tumours." (PMID 32450834, 2020). "Nevertheless, CD99 and PAX8 specificity is limited in ES because its immunoreactivity is commonly observed in many other tumours." (PMID 32675940, 2020). "Our results show a difference in CD99 splicing in activated endothelial cells and EWS tumor cells, which provides opportunities for specific therapeutic targeting to treat cancer." (PMID 31001265, 2019).
tumor (continued). "The expression of relevant molecular biomarkers of both tumor types, analyzed in all PDXs, was also faithfully mirrored by PDX, in particular SATB2 and PGP in OS PDX, CD99 and caveolin 1 in EW PDX." (PMID 31434953, 2019). "Here we show that, as a consequence of CD99 silencing, EWS cells deliver exosomes with oncosuppressive functions that significantly reduce tumor aggressiveness." (PMID 31209202, 2019). "The MFB tumor cells show immunoreactivity for CD34, desmin, and, variably, with smooth muscle actin (SMA), estrogen receptor (ER)/progesterone/androgen receptor, CD99, B-cell lymphoma 2 (Bcl2), and CD10, and they do not express cytokeratins or p63." (PMID 30989009, 2019). "CD34, Bcl-2, and CD99 have been recognized as a representative marker of SFT, but they can also be positive in other neoplasms." (PMID 31520184, 2019). "Both CD99 and CD73 were expressed in tumor cells as well as in fibroblasts, although, more abundant expression was observed in fibroblasts than in tumor cells." (PMID 31510956, 2019). "Although IHC fails to predict the biological behavior of tumors, Ki-67 and CD99 may suggest that tumors are more aggressive, which reminders us that this patient warrants close follow-up because of high proliferation activity of the tumor cells indicated by ki-67." (PMID 31804335, 2019). "Immunohistochemical staining showed a Ki67 index of 8% in the tumour cells, strong and diffuse positivity for CD34 and STAT6, and zonal positivity for vimentin and CD99." (PMID 31228959, 2019). "Using immunoblotting, CD99 and CD73 were expressed by both tumor cells and fibroblasts, when cultured separately." (PMID 31510956, 2019). "The tumour consisted of spindle cells positive for TLE1 and CD99 and for the fusion transcript SS18-SSX determined in routine diagnosis." (PMID 30745580, 2019). "Expression of CD99 was upregulated in growth factor activated HUVEC, resembling tumor endothelial cells, as determined by Western blot analysis." (PMID 31001265, 2019). "All cultures were characterized for tumor surface or stem-like marker expression, namely CD46, CD47, CD55, CD56, CD63, CD90, and CD99." (PMID 28545562, 2017). "Immunohistochemically, the tumor cells stained positively for vimentin, desmin, CD34, ER, and PgR and negatively for S-100, EMA, CK19, CD99, HMB45, and α-smooth muscle actin." (PMID 28831707, 2017). "Immunohistochemically, the tumor cells stained positively for CD34, estrogen receptor (ER), and progesterone receptor (PgR) and negatively for S-100, EMA, CK19, CD99, HMB45, and α-smooth muscle actin." (PMID 28831707, 2017). "Tumor cells are CD34, CD99, and bcl2 positive, while the S-100 protein, actin, and desmin are negative." (PMID 27579199, 2016). "We employed a range of antibodies to characterize the immunophenotype of the tumor cells and found that the tumor cells were positive for CD34, CD99, bcl-2, and vimentin." (PMID 25688313, 2015). "Previous studies have confirmed that tumor markers, including CD34+, Bcl-2+ and CD99+, are generally positive in SFT cases, which has aided the diagnosis of SFTs." (PMID 25452776, 2015). "Immunohistochemistry demonstrated diffuse membrane positivity of the tumor cells for vimentin, FLI1 and CD99 and negativity for CKpan, CgA, Syn, CD117, HMB45, S100, CD20 and CD3." (PMID 25780425, 2015). "Dot-like pan-cytokeratin (CKpan) reactivity near the nucleus, β-catenin reactivity at the cell membrane, diffuse CD99 expression in cytoplasm, and wide CK19 expression in tumor cells were observed." (PMID 25886790, 2015). "After complete surgical removal of the tumor, immunohistochemical analysis revealed strong positivity for the mesenchymal markers vimentin, CD34, CD31 and CD99 in neoplastic cells." (PMID 24758544, 2014).
tumor (continued). "Despite being closer to the primary tumor, this MSC presented comparable levels of CD99 intensity to the other patients." (PMID 24498265, 2014). "Under immunohistochemical examination, the tumor is positive for several neural markers, such as NSE, CD99, and vimentin." (PMID 25404964, 2014). "The patient was referred to radiotherapy ward for further management; immunohistochemistry was performed there in which the tumor cells exhibited NSE and Vimentin along with diffuse membranous staining for CD-99." (PMID 24847440, 2014). "Immunohistochemistry showed that the tumor cells were diffusely positive for CD34, CD99, Bcl-2 and vimentin." (PMID 24179528, 2013). "Immunohistochemical studies show strong staining of the tumor cells with CD34, Bcl-2, CD99, and vimentin." (PMID 23662242, 2013). "Immunohistochemically, the tumor cells were widely positive for vimentin, CD56, CD99 and focally positive for synaptophysin, CD10, progesterone receptor, desmin and CD34, but negative for EMA, cytokeratin, estrogen receptor, S-100 and myoglobin." (PMID 23217062, 2012). "The tumor in our case was positive for CD56, CD99 (to our knowledge the second reported case), synaptophysin and negative for EMA and cytokeratin." (PMID 23217062, 2012). "Most importantly, immunohistochemical staining indicated the positive expression of CD99, S-100, and neuron-specific enolase (NSE) in the tumor cells which supported the diagnosis of rPNET." (PMID 23270507, 2012). "Immunohistochemically, the tumor cells were widely positive for vimentin, CD56, CD99 and focally positive for synaptophysin, CD10, progesterone receptor, desmin and CD34, but negative for EMA, cytokeratin, estrogen receptor, S-100, GFAP and myoglobin." (PMID 23217062, 2012). "Staining adjacent sections with CD99, a marker for ESFT cells, confirmed that the ALDH-positive cells were indeed tumor cells." (PMID 21085683, 2010). "The strong expression of CD99 and BCL2 in the tumour cells further supports the diagnosis of SFT, but as stand-alones these markers would not be sufficient." (PMID 17118185, 2006). "Immunohistochemistry revealed strong expression of CD34, CD99, BCL2 and vimentin in virtually all tumour cells." (PMID 17118185, 2006). "The IHC staining was positive for CD99 and FLI-1 (in >50% of tumor cells) and negative for AE1/AE3, INI-1 loss, WT1, desmin, myogenin, BCOR, TLE-1, CD45CLA, and synaptophysin." (PMID 41230381, 2026). "Targeted immunohistochemistry showed tumor cell positivity for cytokeratin, nuclear beta-catenin, CD56, dot-like CD99, progesterone receptor (focal), and aberrant focal CD31 expression, with negativity for ERG and other vascular markers, confirming the diagnosis of SPN." (PMID 41859616, 2026). "The tumor was positive for CD99, SATB2, TLE1, cyclin D1, and focal FLI1, while negative for EMA, S100, desmin, calponin, and SOX10." (PMID 41869091, 2026). "Thirdly, the tumor’s morphology did not resemble the typical small round cell sarcoma, despite strong CD99 expression and patchy NKX2.2 positivity." (PMID 41426942, 2025). "CD99 is a transmembrane protein, also known as MIC2, which was originally identified in human leukaemia cells and is thought to be a marker for the recognition of tumour cells." (PMID 40356050, 2025). "The tumor was successfully excised via an endonasal endoscopic approach, and histopathological analysis confirmed the diagnosis of an SFT with positive CD34 and CD99 markers." (PMID 40709355, 2025). "The exact mechanism by which CD99 functions as a tumor promoter or suppressor in different cancer types has not been completely elucidated." (PMID 40427525, 2025). "A recent paper demonstrated that EWS-FLI1 and CD99 simultaneously inhibit miR-214-3p function, leading to a failure to inhibit High-mobility group protein A1 (HMGA1) protein, thereby maintaining the undifferentiated state and tumor aggressiveness." (PMID 40427525, 2025).
tumor (continued). "Additionally, we observed significant enrichment of signaling pathway interactions, including CD99, IFN-II, and CD80, in tumor-reactive (TR) CD8 + T cells." (PMID 40855305, 2025). "In the MMRd subtype, non-inflamed phenotypes exhibited upregulation of CD99 and NLGN1, both of which have been implicated in immune suppression and tumor progression." (PMID 39751650, 2025). "Immunohistochemically, tumor cells express TLE1, EMA, CK19, and some cases could express S-100, CD99, and Bcl-2." (PMID 40826697, 2025). "In EWS, CD99 engagement induces tumor cell death through a unique, non-conventional, caspase-independent programmed cell death involving zyxin and actin as mediators of this process." (PMID 40427525, 2025). "Additionally, the tumor cells were strongly positive for CD56 and INI-1, and partially positive for CD99 and vimentin." (PMID 39399175, 2024). "In our study, CD99 exhibited significant upregulation in HG dysplasia and cancer outcome groups while it was undetectable in the NMN group, suggesting it as a driver for cell migration and tumor invasiveness." (PMID 39252972, 2024). "The subsequent immunohistochemical studies were performed, confirming that the tumor was diffusely positive for Calretinin and Inhibin, focally positive for CD99, and negative for CD10." (PMID 38276058, 2024). "We have previously demonstrated that EVs derived from CD99-positive or CD99-negative cells hold a differential microRNAs cargo that influences the behavior of tumor recipient cells." (PMID 38338867, 2024). "Histopathology revealed a cellular tumor comprising tightly packed round to fusiform cells arranged around blood vessels with intervening thick collagen, positive for CD99, vimentin, BCL2, CD34, and STAT6 and negative for EMA, CK AE1/AE3, S100, TLE1, and SMA." (PMID 38606238, 2024). "Tumor cells were positive to vimentin and CD99, but negative to S-100, SMA, HHF-35, desmin, CD31, CD34, STAT-6 and pan-cytokeratin (AE1/AE3)." (PMID 39462411, 2024). "The transcriptomic dynamics of cells with or without expression of EWS::FLI1 or CD99 were analyzed and correlated with tumor cell growth." (PMID 39524141, 2024). "In addition, malignant tumor markers including CD99, NKX2.2, and FLI1 were all highly expressed in tumor cells." (PMID 38769118, 2024). "Tumor cells in case 3 of our study were positive to vimentin and CD99 but they were negative to S-100, desmin, HHF-35, SMA, CD31, CD34, STAT-6 and pan-cytokeratin (AE1/AE3)." (PMID 39462411, 2024). "Many signals favoring tumor cells were significantly activated in C2, such as integrin-related signals (COL9A3 − (ITGA2+ITGB1), JAM3 − (ITGAM+ITGB2), COL6A1 − (ITGA1+ITGB1)), immune suppression signals (CD99 − PILRA), etc.." (PMID 39391717, 2024). "The tumor cells expressed CD99, synaptophysin, CD56, MUC4, and EMA (focal), but not AE1/AE3, S100, smooth muscle actin, desmin, CD34, chromogranin A, GFAP, NKX2-2, PAX7, and INSM1." (PMID 39249507, 2024). "The cell communication pattern of CD99 signaling pathway was displayed by scatter plot, and it could be seen that the tumor epithelial cell subgroup C3 PLP2+ Tumor EPCs had a large number and the highest intensity on CD99 signaling pathway." (PMID 38482016, 2024). "Furthermore, our group also tried to identify tumor-specific antigens for T-ALL CAR T therapy and demonstrated that CD30 and CD99 are potential options for R/R T-ALL cases." (PMID 36680011, 2023). "We carried out therapy with CAR targeting CD99, which has 12E7 scFv, and achieved a significant tumor-killing effect without cytotoxicity to normal cells." (PMID 36680011, 2023). "Immunohistochemically (IHC), tumor cells were positive for SMA, MDM2, and p16; the cells were negative for desmin, MyoD1, Myogenin, pan-cytokeratin, S100, SOX10, HMB45, Malen-A, CD34, CD31, CD99, and ALK." (PMID 37735390, 2023).